IFIH1 (interferon induced with helicase C domain 1)
Diseases named in the same sentence as IFIH1 in open-access papers (continued):
Sharing a sentence is not in itself a finding about the gene and the disease.
type 1 diabetes (continued). "Conversely, a rare genetic variant of the Interferon-Induced with Helicase C Domain 1 (IFIH1) gene, encoding a protein implicated in the host response to viruses and fungi, seems to be protective not only for type 1 diabetes and Ps, as demonstrated a few years ago, but also for PsA." (PMID 29425183, 2018). "These include OAS1, C4A, and IFIH1 for Type 1 diabetes and ID3 and C4 for Sjögren’s syndrome." (PMID 30002654, 2018). "Genotype and allele frequencies of the IFIH1 rs1990760 G/A polymorphism in patients with type 1 diabetes mellitus (T1DM) and nondiabetic subjects." (PMID 24386202, 2013). "The association of each IFIH1 SNP with enterovirus was similar among children with and without the type 1 diabetes-associated HLA DR4-DQ8/DR3-DQ2 high-risk genotype, respectively (data not shown)." (PMID 22110759, 2011). "We conclude that the type 1 diabetes-associated IFIH1 polymorphisms have no, or only minor influence on the occurrence, quantity or duration of enterovirus infection in the gut." (PMID 22110759, 2011). "This probably reflects the fact that most individuals with type 1 diabetes display signs of EV infection in pancreatic islets, and that the effect of the variant in IFIH1 may be more nuanced than simply the presence or absence of VP1 positivity in islets." (PMID 35867130, 2022). "Genetics have a crucial role in the susceptibility of diabetes type 1; the most common genes related to type 1 diabetes are CTLA-4, PTPN22, STAT4, STAT3, and IFIH1." (PMID 34342790, 2021). "Furthermore, taking all these five IFIH1 polymorphisms into account did not influence our previously reported lack of association between enterovirus frequency and risk of islet autoimmunity in children with the type 1 diabetes susceptibility HLA-DR4-DQ8/DR3-DQ2 genotype." (PMID 22110759, 2011). "In our recent study of individuals with type 1 diabetes and control individuals, enterovirus RNA was found significantly more often in peripheral blood mononuclear cell (PBMC) subsets than in plasma and virus detection correlated with islet autoimmunity and the IFIH1 genotype." (PMID 40095061, 2025). "After testing of 46,939 Norwegian newborns, 421 children carrying the high risk genotype for type 1 diabetes (HLA-DR4-DQ8/DR3-DQ2) as well as 375 children without this genotype were included for monthly fecal collections from 3 to 35 months of age, and genotyped for the IFIH1 polymorphisms." (PMID 22110759, 2011).
Aicardi-Goutières syndrome (55 papers, 2015 to 2025). "Mutations in ADAR1 (Adenosine deaminase acting on RNA 1) and IFIH1 (Interferon Induced With Helicase C Domain 1) are associated with Aicardi-Goutières syndrome (AGS), a genetically determined inflammatory disorder particularly affecting the brain and skin." (PMID 41351966, 2025). "Mutations in IFIH1 have been associated with Aicardi-Goutières syndrome and Singleton-Merten syndrome, both of which have similar overlapping features and are associated with glaucoma." (PMID 38272457, 2024). "In case series including patients with Aicardi-Goutieres syndrome, which carry mutations in the IFIH1 gene, the efficacy of JAK-inhibitors in ameliorating skin and systemic manifestations have been reported." (PMID 35211430, 2022). "Mutation of IFIH1 gene encoding MDA5 can lead to a rare neurological disorder Aicardi–Goutières syndrome (AGS), which is characterized by abnormal production of type I IFN." (PMID 36119095, 2022). "IFIH1 gain-of-function has been reported as a cause of a type I interferonopathy encompassing a spectrum of autoinflammatory phenotypes including Aicardi–Goutières syndrome and Singleton Merten syndrome." (PMID 31898846, 2020). "It was reported that IFIH1 mutations resulted in the aberrant induction of type I interferon, which was an etiology of Aicardi-Goutières syndrome." (PMID 29028840, 2017). "The IFIH1 R779H mutation is known to cause Aicardi-Goutières syndrome (AGS)." (PMID 41026253, 2025). "Similarly, in humans, mutations in both ADAR1 and MDA5 (also known as IFIH1) are known to cause Aicardi-Goutières syndrome, a devastating inflammatory autoimmune disease." (PMID 35041722, 2022). "Additionally, mutations in IFIH1/MDA5 are associated with Singleton-Merten Syndrome and with Aicardi-Goutières syndrome." (PMID 33498715, 2021). "In addition, IFIH1 mutations cause rare disorders such as Singleton–Merten syndrome and Aicardi–Goutières syndrome (AGS)." (PMID 34439917, 2021). "In addition, a family presenting with varying skin and neurological phenotypes diagnosed as Aicardi-Goutières syndrome (AGS) with overlapping SMS features was reported to have a different heterozygous missense mutation in IFIH1 determined by whole-exon sequencing." (PMID 28955379, 2017). "The gain of function mutations of DDX58 and IFIH1, which encode RIG-I and MDA5, respectively, are reported in studies on whole-exome sequencing in patients with Singleton–Merten syndrome (SMS) and Aicardi–Goutieres syndrome (AGS)." (PMID 32708595, 2020). "IFIH1 (encoding MDA5) mutations reportedly result in aberrant type I IFN expression, leading to AGS (Aicardi–Goutières syndrome), an inflammatory disease characterized by cerebral atrophy, leukoencephalopathy, intracranial calcifications, and chilblain skin lesions." (PMID 38343534, 2024). "Aberrant activation of non‐canonical inflammasome factors has been associated with a range inflammatory pathologies; for instance, a case of a 10‐year‐old girl diagnosed with Aicardi‐Goutières syndrome (AGS), positive for heterozygous IFIH1 mutation (c.2336G > A (p.R779H))." (PMID 35832835, 2022). "Certainly in the autoimmune vasculitis variants known as Aicardi-Goutières syndrome, where altered degradation of cytosolic DNA or RNA is caused by mutations in TREX1/SAMHD1/RNASEH2A/B/C/ADAR/IFIH1/PNPT1, the progressive immune activation leads to phenotypes of neuro-inflammation/-degeneration." (PMID 34345994, 2021). "Interestingly, one form of Aicardi-Goutières Syndrome caused by activating mutations in IFIH1, the gene that encodes MDA5, alters the function of MDA5 so mutant MDA5 now recognizes Alu:Alu inverted repeats with imperfect sequence homology." (PMID 33969287, 2021). "Aicardi-Goutieres syndrome (AGS) is an early-onset encephalopathy that can be caused by a gene mutation in one of 7 discovered genes so far (TREX1, RNASEH2B, RNASEH2C, RNASEH2A, SAMHD1, ADAR1, and IFIH1)." (PMID 32737687, 2020).
Aicardi-Goutières syndrome (continued). "Aicardi-Goutieres syndrome is classified as a monogenic interferon disease resulting from an aberrant mechanism involving intracellular nucleic acid sensing mediated by TREX1, RNASEH2A, RNASEH2B, RNASEH2C, SAMHD1, ADAR1 or IFIH1." (PMID 39286150, 2024).
psoriasis (41 papers, 2011 to 2025). An autoimmune condition characterized by red, well-delineated plaques with silvery scales that are usually on the extensor surfaces and scalp. "Second, vitiligo and psoriasis share some common susceptibility genes (e.g., IFIH1, BTNL2) and genetic loci (e.g., HLA-C/HLA-B rs9468925)." (PMID 40156617, 2025). "The association between psoriasis and several IFIH1 variants, either isolated or interacting with other gene variants, has been previously reported." (PMID 37834254, 2023). "In this study, we verified the psoriasis susceptibility genes IFIH1 (2q24.3), ERAP2 (5q15), IL18R1 (2q12.1), LTBR (12p13.31), IL1RL1 (2q12.1), CARD14 (17q25.3), and SLC9A4 (2q12.1)." (PMID 36425068, 2022). "Psoriasis was described in two families with prominent musculoskeletal manifestations associated with IFIH1 mutations at residue 331 (T331I and T331R)." (PMID 32508843, 2020). "We observed associations between the viral receptor IFIH1 and 10 phenotypes including protective effects against hypothyroidism, hypertension, gastric reflux, and psoriasis." (PMID 29691392, 2018). "Our investigation of alleles at the low end of the frequency spectrum with variant aggregation tests has expanded our understanding of the allelic architecture of psoriasis risk at the IFIH1 and TYK2 loci." (PMID 28973304, 2017). "Several recently identified single-nucleotide polymorphisms (SNPs) that are linked to psoriasis susceptibility are found adjacent or in close proximity to genes associated with the innate immune response, such as IFIH1 (MDA5), NFKBIA, STAT3, and SOCS1." (PMID 25658361, 2015). "We found that rs10484554 and rs12191877 near HLA-C and rs17716942 near IFIH1 were associated with age of psoriasis onset with false discovery rate < 0.05." (PMID 24175098, 2013). "Larger studies are needed to evaluate the contribution of other risk alleles, including IFIH1, to age of psoriasis onset." (PMID 24175098, 2013). "We found that rs10484554 and rs12191877 near HLA-C and rs17716942 near IFIH1 were associated with age onset of psoriasis with FDR_q value < 0.05." (PMID 24175098, 2013). "We confirmed the known relationship between the HLA-Cw6 allele and type I disease (early, familial, and severe), while PsA was independently and positively associated with female sex, severe psoriasis, and the IFIH1/MDA5 rs1990760 TT variant, but negatively with HLA-Cw6." (PMID 38337541, 2024). "IFIH1 gene, which encodes the cytosolic viral RNA receptor that activates type I interferon signaling, is considered a risk factor for various AIDs, including classical psoriasis." (PMID 39840076, 2024). "We investigated the association of three IFIH1 SNPs with the onset age of psoriasis and PsA." (PMID 37834254, 2023). "In the case of IFIH1, the rs1990760 SNP was linked to psoriasis susceptibility." (PMID 37569685, 2023). "The association between IFIH1 variants and psoriasis has been supported by some studies." (PMID 37834254, 2023). "Our aim is to investigate the association of the IFIH1 rs1990760, rs35744605, and rs35337543 SNPs and the risk of developing psoriasis and whether these variants have a significant effect on onset age, disease severity, and the risk of PsA." (PMID 37834254, 2023). "Interestingly, in agreement with our results, the IFIH1 alleles associated with increased risk of psoriasis were also associated with younger onset age by others." (PMID 37834254, 2023). "Interestingly, individuals with missense variants in Human MDA5 gene (IFIH1) are protected from psoriasis and gain of function MDA5 mutations have related type I interferonopathy with musculoskeletal disease that includes psoriasis." (PMID 32595643, 2020). "Psoriasis was also reported to be associated with rare missense variants in the IFIH1 gene locus." (PMID 30761886, 2019).
psoriasis (continued). "In line with this view, loss-of-function variants of IFIH1 were identified as protective alleles for psoriasis and psoriatic arthritis, perhaps explaining why gain-of-function mutations may increase the risk for developing psoriasis." (PMID 32508843, 2020). "Most gene-disease pairs displayed deleterious associations, except IL33-asthma (0.99, P = 8.09 × 10−16) and IFIH1-psoriasis (0.98, P = 1.02 × 10−6)." (PMID 39009607, 2024). "IFIH1 gene variants that increase MDA5 activity have been associated with an increased risk for immune-mediated diseases, including psoriasis." (PMID 37834254, 2023). "In summary, we screened for interactions between genes that affect psoriasis susceptibility and found that the most significant interaction was between the rs27044 polymorphism of ERAP1 and the rs7590692 polymorphism of IFIH1." (PMID 36425068, 2022). "IFIH1 has been related to psoriasis in a European population (rs17716942), and its rs35667974 and rs10930046 polymorphisms were found to have protective effects against psoriasis in a white North American population." (PMID 36425068, 2022). "Our case highlights phenotypic heterogeneity of AGS and describe psoriasis and ILD as part of the clinical spectrum associated with gain-of-function IFIH1 mutations." (PMID 32508843, 2020). "Functional studies suggest that rs1990760-C (p.T946A) causes IFIH1 loss-of-function (LOF), and additional IFIH1 LOF alleles have been shown to protect against T1D, vitiligo, psoriasis, and psoriatic arthritis (PsA)." (PMID 30327483, 2018). "Since IFIH1 and TYK2 are located in known psoriasis susceptibility loci, we further scrutinized genes in all previously reported psoriasis susceptibility loci." (PMID 28973304, 2017). "Both IFIH1 and TYK2 are located in loci previously implicated in common variant studies of psoriasis risk." (PMID 28973304, 2017). "Nevertheless, 7 of the PP-increased DEGs were associated with psoriasis susceptibility loci (LCE3D, IFIH1, GRHL3, IL12B, PRSS53, REL and NOS2), and 1 PP-decreased DEG was near a psoriasis susceptibility locus (SDC4)." (PMID 24260178, 2013). "Several studies have investigated the role of IFIH1/MDA5 in psoriasis." (PMID 37834254, 2023). "The genes associated with psoriasis that encode IFNs and IFN mediators are IFN-γ and IFIH1." (PMID 37569685, 2023). "Taken together, these molecular biological findings suggest that ERAP1 might regulate the expression of IFIH1, but more basic biological studies are needed to determine how this gene interaction affects psoriasis." (PMID 36425068, 2022). "Increased expression levels of IFIH1 have been observed in psoriasis skin lesions compared with healthy skin, suggesting that pharmacological inhibition of this gene could be effective in treating psoriatic disease." (PMID 28501801, 2017). "Psoriasis severity (OR: 2.14), female sex (OR: 1.63), and the IFIH1/MDA5 rs1990760 TT genotype (OR: 1.62) were significantly related to PsA, while HLA-Cw6 was protective (OR: 0.65)." (PMID 38337541, 2024). "The top five major signalling pathways in the psoriasis blood dryness group included interferon signaling, GAB1 signalosome, negative regulators of DDX58/IFIH1 signaling, negative regulation of binding, ubiquinone and other terpenoid-quinone biosynthesis." (PMID 35126107, 2021).
ZIKV infection (33 papers, 2016 to 2026). "It should be noted that ZIKV infection in association with obesity, induced a decrease in the transcriptional RIG-I, IFIH1, and IRF3 expression in the placental tissue, compared to the non-obese group." (PMID 36851534, 2023). "Interestingly, obesity, when associated with ZIKV infection, showed a decreased transcriptional expression of RIG-I and IFIH1 (MDA-5 protein precursor gene)." (PMID 36851534, 2023). "Yet, combined transfection of siRNAs directed towards all three different target ISGs (IFIH1, TMEM2, and IFITM3) induced a significant increase in ZIKV replication in pDCs, consistent with an important role of these ISG for restriction of ZIKV infection in pDC." (PMID 32415086, 2020). "Interestingly, we observed a decreased expression of RIG-I and IFIH1, the MDA-5 protein precursor gene, in the placental tissue of the mothers with obesity (p = 0.0249; p = 0.0108, respectively), compared to the non-obese group, during ZIKV infection." (PMID 36851534, 2023).
diabetes (30 papers, 2011 to 2024). "Further supporting the significance of IFIH1 in diabetes pathogenesis, a variant of IFIH1, rs1990760 was revealed as one of the top non-synonymous single-nucleotide polymorphisms (SNPs) associated with T1D." (PMID 38487540, 2024). "The IFIH1 gene has been associated with the pathogenesis of diabetes (type 1 and type 2) and multiple autoimmune diseases." (PMID 36979105, 2023). "The partial loss of Ifih1 in mice with a B6 background and complete deficiency of Ifih1 in mice with a 129/SvJ background led to the development of transient hyperglycemia and overt diabetes after infection with 1 × 103 PFU of EMCV-D, respectively." (PMID 32727064, 2020). "Since the outcome of virus-induced diabetes is influenced by many factors including viral diabetogenicity and host susceptibility, the discovery of other risk genes associated with virus-induced diabetes in addition to IFIH1 and TYK2 genes is both possible and feasible." (PMID 26288847, 2015). "Decreased expression of IFIH1 was found to significantly decrease diabetes incidence in NOD/ShiLtJ (NOD) mice, a spontaneous mouse model for T1D." (PMID 38487540, 2024). "Since the rs1990760 IFIH1 risk variant is associated with increased susceptibility to T1D, we set out to determine how IFIH1R alters the immune system by promoting diabetes pathogenesis in vivo by utilizing an Ifih1R knock-in model on the NOD mouse strain." (PMID 38487540, 2024). "Ten- to twelve-week-old female NOD mice heterozygous for the Ifih1 gene showed complete protection against the onset of diabetes following CVB4 infection, in contrast to their wild-type littermates in which the incidence of diabetes reached 50%." (PMID 32727064, 2020). "While diabetes is a rare feature of monogenic interferonopathies, two loci within the IFN pathway (IFIH-1 and TYK2) have been robustly associated with polygenic T1D." (PMID 30888520, 2019). "Children with the IFIH1 rs2,111,485 GG genotype had a faster progression to diabetes (31% within 5 years) than children with the T1D protective GA or AA genotypes (11% within 5 years)." (PMID 28829396, 2017). "Furthermore, the NOD.Ifih1 mice present a unique opportunity to investigate how immune-response changes contribute to diabetes." (PMID 38487540, 2024). "T1D risk in a cohort of DAA revealed that diabetes risk was associated with the IFIH1 rs2,111,485 SNP, but did not associate with the development of islet autoantibodies or autoantibodies against thyroid peroxidase and tissue transglutaminase." (PMID 28829396, 2017). "Consistent with the notion that elevated expression and/or activity of IFIH1 may drive diabetes progression, our previous work demonstrated the Ifih1A946T risk variant (Ifih1R) behaved as a gain-of-function variant, which elevated basal expression and poly(I:C)-induced levels of IFN I." (PMID 38487540, 2024). "In age-at-onset and diabetes duration adjusted models, RELA/11q13 and FCRL3/1q23 SNPs were associated with IA-2A positivity, LPP/3q28 SNPs were associated with GADA positivity, and IFIH1/2q24 was associated with positivity for autoantibodies related to autoimmune gastritis and thyroid disease." (PMID 36181724, 2022). "Consistent with such a role of IFIH1, non-obese diabetic (NOD) mice with homozygous Ifih1 knockout are fully protected from spontaneous diabetes, whereas NOD mice with heterozygous Ifih1 knockout are partially protected." (PMID 28212332, 2017).
idiopathic inflammatory myopathy (28 papers, 2014 to 2026). Idiopathic form of inflammatory myopathy. "Single-nucleotide polymorphisms (SNPs) in the TNFAIP3, IFIH1, and IRF5 genes have been associated with several auto-inflammation diseases, while the susceptibility between these genes and idiopathic inflammatory myopathies (IIMs) were not reported." (PMID 25337792, 2014).
rheumatoid arthritis (22 papers, 2007 to 2026). A chronic, systemic autoimmune disorder characterized by inflammation in the synovial membranes and articular surfaces. "Genes showing lower levels of expression in AD included ICAM-1, IL-1B, CCR1, IFIH1, SOCS1, TNFAIP3 and TNFSF13B, which are strongly associated with acute and chronic inflammation and adult rheumatoid arthritis." (PMID 26310571, 2015).
influenza (20 papers, 2012 to 2025). An acute viral infection of the respiratory tract, occurring in isolated cases, in epidemics, or in pandemics; it is caused by serologically different strains of viruses (influenzaviruses) designated A, B, and C, has a 3-day incubation period, and usually lasts for 3 to 10 days. "In influenza patients, the interferon pathway-related genes IFI44, IFI6, IFIH1, STAT1, and GBP1 also showed overexpression, while no obvious interferon transcriptional signature was observed in AECOPD and CAP." (PMID 36059536, 2022).